IL4I1 (interleukin 4 induced 1)
Diseases named in the same sentence as IL4I1 in open-access papers (continued):
Sharing a sentence is not in itself a finding about the gene and the disease.
tumor (continued). "The in vivo effect of IL4I1 expression on tumor growth and the anti-tumor immune response has currently been studied in only a limited number of models." (PMID 39211039, 2024). "The study also demonstrated that neutralisation of IL4I1 activity can block tumour cell migration and restore effective anti-tumour immunity." (PMID 39120301, 2024). "IL4i1 is released by tumor cells, potentially contributing to the production of host immune tolerance." (PMID 37296860, 2023). "Both transcriptome and protein levels of IL4I1 were increased obviously in various tumor types, and correlated with a dismal prognosis." (PMID 38250074, 2023). "Being it is highly expressed in tumor-associated macrophages (TAMs), IL4i1 activity and its products reduce the activity of anti-tumor CD8+ T cells, enhancing tumor escape." (PMID 37296860, 2023). "As the L-amino acid oxidase, IL4I1 modulated amino acid metabolism, which is the pivotal nutrient of many tumor-infiltrating immune cells." (PMID 37434155, 2023). "In summary, we demonstrated notable upregulation of IL4I1 expression across various tumor tissues, which correlated with an unfavorable prognosis." (PMID 38250074, 2023). "The degradation of Tryptophan to Kynurenine is catabolized by tryptophan enzymes, including IDO1, IDO2, TDO2, and IL4I1, which up‐regulate PD‐L1 expression and promote tumor suppressive microenvironment in various cancers." (PMID 37148546, 2023). "We analyzed data from TCGA and found that IL4I1 was positively correlated to metastasis, poor prognosis and more immune infiltrates in tumor microenvironment." (PMID 37434155, 2023). "Nevertheless, it is interesting to note that according to the TCGA dataset covering more than 500 H&N cancer patients, IL4I1 is significantly more than two‐fold overexpressed in tumour tissue than in normal ones." (PMID 38117000, 2023). "Specifically, indole-3-pyruvic acid (I3P) and indole-3-aldehyde (I3A) catalyzed by IL4I1 in tumor activated AHR signaling through receptor-ligand binding, leading to increased motility of cancer cells and diminished proliferation of cytotoxic CD8+ T cells." (PMID 37507432, 2023). "In tumor microenvironments, IL4i1 and IDO1 have overlapping expression patterns, especially in myeloid cells, suggesting the two enzymes control a network of tryptophan-specific metabolic events." (PMID 37196768, 2023). "We evaluated the IHC staining of Trp‐catabolizing enzymes, including IDO1, IDO2, TDO2, and IL4I1, in tumor cells." (PMID 37148546, 2023). "As an immunosuppressive enzyme, IL4I1 plays an important role in tumor immune escape and predicts poor prognosis." (PMID 37434155, 2023). "Analyses based on data from TCGA, Rembrandt, GSE16011, and CGGA datasets consistently indicated a noticeable increase in IL4I1 levels with higher tumor grades, particularly in WHO grade IV compared with grades II and III." (PMID 38250074, 2023). "For the first time, we revealed the patterns of IL4I1 expression and its role across 33 tumor types, focusing on the difference in both mRNA and protein expression within normal and tumor tissues, and evaluated prognostic significance of IL4I1 expression." (PMID 38250074, 2023). "Since IL4I1 has been reported to have immunoinhibitory effects and tumor‐promoting effects in several cancer types, the development of IL4I1‐targeted drugs will provide a novel strategy for the treatment of numerous cancer types." (PMID 37655051, 2023). "Some researchers showed that the tumor tissues expressing IL4I1 biologically has a good prognosis with overexpression of IL4I1." (PMID 37434155, 2023). "Tumor cells produce large amounts of the IL4I1 metabolic enzyme, which promotes the spread of tumor cells and suppresses the immune system." (PMID 38140587, 2023).
tumor (continued). "IL4I1 shows enhanced expression in a wide variety of tumor types, and its Trp-metabolizing activity yields various downstream metabolites which are associated with AhR agonism, including I3LA, I3AA, I3A and KynA." (PMID 36765849, 2023). "What’s more, immunoregulatory enzymes, such as IDO1 and IL4I1, also created and sustained the tumor-tolerant microenvironment, which is expressed either by the tumor cells or by immune cells." (PMID 37434155, 2023). "HES1+ TAMs and TREM2+ TAMs were preferentially located in the tumor tissue while IL-4I1+ TAMs were enriched at the tumor periphery." (PMID 36845555, 2023). "Consistent with data from previous studies, these findings proved the critical effect of IL4I1 in diverse tumor types, emphasizing the potential of developing IL4I1-targeting inhibitors as a prospective and broad-spectrum avenue for cancer therapy." (PMID 38250074, 2023). "The results indicated that five of seven methylated CpGs of IL4I1 (cg06388099, cg05934682, cg03166835, cg24160312, and cg10805880) exhibited significant reductions with increasing tumor grade, and were lower in WHO III compared with WHO II." (PMID 38250074, 2023). "In the present study, we consistently observed that the PD-1, T-cell receptor, and tumor escape from immune attack signaling pathways were significantly enriched in CM samples with high IL4I1 expression." (PMID 36466837, 2022). "An important feature of cancer biology is the identification of IL-4I1 (L-Phe oxidase) as a metabolic immune checkpoint that activates the AhR and promotes tumour progression by enhancing cancer cell motility and suppressing adaptive immunity." (PMID 36286592, 2022). "In the context of cancer, IL4I1 is expressed by infiltrating macrophages and occasionally by the tumor cells." (PMID 36131918, 2022). "IL4I1 inhibited the proliferation of T cells including CD8 + anti-tumor T cells and recruited suppressor immune cells such as Tregs by activating Aryl hydrocarbon receptor (AHR)." (PMID 36118894, 2022). "Addressing other mediators of tumour activity related to Trp metabolism, notably activation of the AhR, IL-4I1, PARPs and SIRTs will be equally important, with AhR inhibition being a priority." (PMID 36286592, 2022). "On the other side, the expression of interleukin-4induced-1 (IL4I1) in tumors has also been observed very frequently, especially in tumor-associated macrophages." (PMID 35778697, 2022). "In mouse tumor models, IL4I1 facilitates escape from the immune response and in humans, its local expression correlates with decreased survival and a pejorative outcome." (PMID 36131918, 2022). "Among the 6 hub FAMGs, IL4I1 (interleukin-4-induced gene 1) has a vital role in immunosuppressive functions and tumor immune escape." (PMID 36466837, 2022). "further showed that IL4I1 stimulates the generation of Foxp3+ regulatory T cells and limits T helper 1 and T helper 2 polarization in vitro, and their findings reinforced the concept that IL4I1 facilitates tumor escape from the immune response." (PMID 36466837, 2022). "IL4I1, an important gene in Riskscore model, was reported to play important roles in immunoregulation and tumor progression." (PMID 34717685, 2021). "Compared to tumor-free mice, it turned out to be that IL4i1 was among the most upregulated genes in tumor-supportive monocytes." (PMID 33692337, 2021). "In fact, although IL4I1 drives the motility of tumor cells, immune modulation is the most enriched function of IL4I1." (PMID 33692337, 2021). "IL4I1 was strongly detected in the tumor bed of most human tumor types and was identified as a prognostic biomarker." (PMID 34717685, 2021). "Interleukin-4 Induced gene 1 (IL4I1), an important gene in Riskscore model, was reported to play important roles in immunoregulation and tumor progression." (PMID 34717685, 2021).
tumor (continued). "According to some relevant paper, the role of IL4I1 in escaping tumor immune response can be achieved by participating in the fine control of adaptive immune of B and T cells." (PMID 34604392, 2021). "Conversely, IL4i1−/− chimeras mice reduced tumor burden, indicating the role of IL4I1 in immune escape." (PMID 33692337, 2021). "By enhancing systemic Trp-catabolism, IL4I1 contributed to a systemic tumor-promoting environment that allowed tumor cells to migrate and protected them from immune destruction." (PMID 34717685, 2021). "In a model of the adoptive transfer of tumor cells expressing the enzyme or not, the incidence of tumor development was enhanced and the CD8+ T-cell response against tumor antigens was diminished by IL4I1." (PMID 31330829, 2019). "This study identified IL4I1 as a marker of macrophage infiltration, as the oxidase was expressed by tumor-infiltrating macrophages in almost all tumors analyzed." (PMID 31330829, 2019). "Such expression, associated with its capacity to facilitate tumor growth by inhibiting the anti-tumor T-cell response, makes IL4I1 a new potential druggable target in the field of immunomodulation in cancer." (PMID 29206151, 2017). "By contrast, IL4I1 is highly expressed in TAMs and can promote tumor escape by inhibiting CD8+ antitumor T cell response." (PMID 26599209, 2015). "In human, it was proved that IL4I1 improve tumor growth by inhibiting the CD8(+) antitumor T-cell response." (PMID 22860004, 2012). "The role of IL4I1 in tumor progression has become increasingly complex." (PMID 41008831, 2025). "Additionally, TAM from the tumor tissues of R/R DLBCL patients were found to express significantly higher level of Interleukin 4 Induced 1 (IL4I1) compared to responders." (PMID 41219641, 2025). "This dual role of IL4I1 underscores its complex regulatory mechanism in tumor development." (PMID 41008831, 2025). "Our analysis revealed that IL4I1 is predominantly expressed in fibroblasts, with minimal expression observed in CD8+ exhausted T cells (CD8Tex), suggesting that IL4I1 may play a role in tumor immune suppression." (PMID 41008831, 2025). "Both IDO1 and IL4I1 were expressed by HNSCC tumor cells in the TMA." (PMID 40332319, 2025). "Similarly, IL4I1 has been shown to suppress T cell activation and promote immune escape in various tumor types." (PMID 40243888, 2025). "Taken together, our study contributes to the growing evidence that IL4I1 may modulate the tumor microenvironment and influence cancer aggressiveness." (PMID 41008831, 2025). "Our study found that both I3A and IAA were accumulated in IL4I1‐overexpressing tumor cells." (PMID 40583248, 2025). "Furthermore, the tumour volume in MRI was significantly larger in the group with higher IL4I1 levels compared with that in the other groups." (PMID 40071723, 2025). "In our study, IL4I1 was highly expressed in tumors and was notably more abundant in the cancer-immune zone of treatment-sensitive samples, consistent with its role in promoting tumor progression and suppressing anti-tumor immunity." (PMID 40083932, 2025). "Additionally, this pattern was consistent across different cancer stages, indicating that IL4I1 expression increases progressively with disease advancement, suggesting a potential role in tumor progression." (PMID 41008831, 2025). "In this study, IDO1 and IL4I1 were expressed by HNSCC tumor cells in the TMA of 402 patients." (PMID 40332319, 2025). "To verify whether the T cells activation effect of IL4I1‐expressing tumor cells depends on IL4I1 enzyme activity, we next constructed a K351A mutant, the enzyme‐dead mutant form of IL4I1, and overexpressed it on EG7 cells." (PMID 40583248, 2025). "Furthermore, IL4I1 is a potential prognostic biomarker and provided a novel anti‐tumour therapeutic target for GBM." (PMID 40071723, 2025).
tumor (continued). "Moreover, overexpression of the Trp metabolic enzyme interleukin‐4‐induced gene‐1 (IL4I1) in tumor cells increases the intracellular level of I3A and enhances tumor immunogenicity." (PMID 40583248, 2025). "Immune profiling revealed increased immunosuppressive tumor-associated macrophages (e.g., IL4I1, HES1) and monocyte-recruiting chemokines in non-responders." (PMID 40097400, 2025). "Furthermore, we also identified IL4I1 as a potential prognostic biomarker and provided a novel anti‐tumour therapeutic target for GBM." (PMID 40071723, 2025). "Therefore, exploring the relationship between IL4I1 and TAM is helpful in understanding the role of IL4I1 in tumor progression." (PMID 38691253, 2024). "A study showed that IL4I1 + macrophages were associated with tumor cell phagocytosis and predicted a positive prognosis for colon cancer patients, whereas SPP1 + macrophages were associated with hypoxia and necrotic tumor areas and predicted a poor prognosis." (PMID 39068459, 2024). "Whereas only few inhibitors of IL4I1 have yet been disclosed, the preclinical inhibitor CB-668 has demonstrated both monotherapeutic efficacy and favorable combinatorial efficacy with α-PD-L1 therapy in tumor-bearing mice." (PMID 39211039, 2024). "Interleukin-4 inducible gene 1 (IL4I1) regulates tumor progression in numerous tumor types." (PMID 38691253, 2024). "Moreover, IL4I1 is expressed by human Th17 and Th17-like cells and is found in MDSCs of tumor-bearing mice." (PMID 39211039, 2024). "Additionally, IL4I1 induces the production of indole-3-pyrubate (I3P), effectively scavenges free radicals in tumor cells, and inhibits oxidative stress and ferroptosis." (PMID 38853203, 2024). "Among solid and non-B-cell malignancies, IL4I1 is only rarely expressed by tumor cells, but instead can often be found in tumor-associated macrophages." (PMID 39211039, 2024). "While this is corroborated by the ability of IL4I1 to activate the AhR in various models and the high expression of IL4I1 in cancer tissues, it is argued by another study demonstrating only poor correlation between the expression of IL4I1 and individual AhR target genes in a number of tumor types." (PMID 39211039, 2024). "The available findings suggest that IL4I1 changes the anti-tumor CD8+ T-cell response, promotes cancer growth, affects patient survival, and may inhibit immune checkpoint inhibitor therapeutic efficacy." (PMID 38755125, 2024). "Finally, in a model of Lewis lung carcinoma, IL4I1 knock-out inhibits tumor growth and increases the proportions of CD8+ T cells and pro-inflammatory macrophages, while decreasing the proportion of regulatory T cells and immunosuppressive macrophages." (PMID 39211039, 2024). "Thus, we assayed the correlation of IL4I1 expression with infiltrating immunocytes around the tumor cells to investigate the changes in the tumor immune microenvironment." (PMID 37434155, 2023). "Analysis of the gene ontogenies of AHR-associated modules containing IL4I1 in tumors suggests that the IL4I1-AHR axis may promote tumor growth and metastasis through tumor cell-intrinsic and paracrine mechanisms." (PMID 37394584, 2023). "However, most non‐mediastinal DLBCL cases are IL4I1‐negative, with only a minority of cases (17%) exhibiting occasional IL4I1‐positive tumor cells." (PMID 37148546, 2023). "Therefore, IL4I1 was considered to regulate the proliferation, differentiation and function of tumor cells by immune escape." (PMID 37434155, 2023). "Moreover, IL4I1 expression visibly increased with the tumor grade, showcasing higher levels in WHO grade IV compared with grades II and III." (PMID 38250074, 2023).
tumor (continued). "Notably, IL4I1 can activate AHR ligands in tumor cells via tryptophan metabolism, which in turn supports IL-22 production in ILCs." (PMID 37160121, 2023). "Indeed, IL4I1 overexpression is frequent in the tumor microenvironment of cancer patients and has been be correlated to a worsen outcome." (PMID 36131918, 2022). "By thus generating derivatives of tryptophan that activate AHR, IL4I1 may have a role to play in anti-inflammatory responses, as well as in a tumor escape mechanism that reduces survival in cancer patients." (PMID 35295226, 2022). "Moreover, myeloid cells in the TME can release interleukin-4-induced-1 (IL4i1), a secreted amino acid oxidase that mediates the production of indole-3-pyruvate (I3P) from tryptophan, to thus block ferroptosis and support tumour growth." (PMID 34685679, 2021). "The new functions of IL4I1 on the recruitment of MDSCs and Tregs in tumor have also been explored." (PMID 33692337, 2021). "In particular, the chemical blockade of IL4I1 activity in patients with cancer may contribute to the restoration of specific anti-tumor immune responses." (PMID 31330829, 2019). "Conversely, during the development of cancer, infiltration of the tumor microenvironment by IL4I1-secreting cells may help with tumor cell escape from the immune response." (PMID 31330829, 2019). "For example, the chemical inhibition of IL4I1 activity may represent a new adjuvant strategy for the treatment of cancer by restoring specific anti-tumor immune responses." (PMID 29206151, 2017). "Indeed, expression of IL4I1 in transplanted tumors or in a mouse model of spontaneous melanoma correlates with a diminished anti-tumor immune response, reduction of the T cell infiltrate, and enhanced aggressiveness of the tumor." (PMID 29206151, 2017). "Moreover, IL4I1 has a critical role in tumor evolution, so we screened a selection of molecules and identified several IL4I1 inhibitors." (PMID 26599209, 2015). "Moreover, upregulation of novel Lao1 (interleukin 4-induced 1, IL4I1), which is known to control M2 polarization, was specifically detected in tumor tissues from UBCS039-treated mice via transcriptomic analysis and was verified by real-time PCR and western blotting." (PMID 41530841, 2026). "While our study is based on immunohistochemical expression analysis, these findings support the hypothesis that IDO1 and IL4I1 may cooperatively influence the tumor immune microenvironment, possibly through metabolic reprogramming and immune evasion mechanisms." (PMID 40332319, 2025). "While this correlation does not establish causality, it supports the hypothesis that IL4I1 may contribute to tumor progression." (PMID 41008831, 2025). "Taken together, these results suggest that IL4I1 may play an important role in tumor progression." (PMID 38691253, 2024). "Similarly, AhR signaling may be involved in the IL4I1-induced suppression of tumor cell ferroptosis." (PMID 39211039, 2024). "Although this may partially be compensated for by the considerably higher AhR-activating potency of indole-3-pyruvic acid compared to IDO1-generated metabolites, it remains unclear whether IL4I1 is capable of achieving significant AhR activation in most tumor types." (PMID 39211039, 2024). "Importantly, high expression of IL4I1 typically suggests tumor immunosuppression, which may render immune checkpoint inhibitors unsuitable for treatment." (PMID 38691253, 2024). "The conflicting effects of the IL4I1 enzyme may depend on the tumor context, either deleterious in the context of a chronic inflammation (tumor progression) or anti-tumoral in the context of tumor regression." (PMID 37526660, 2023).